IL5 (interleukin 5)
Diseases named in the same sentence as IL5 in open-access papers (continued):
Sharing a sentence is not in itself a finding about the gene and the disease.
asthma (continued). "Despite being hypothetical, this can beachieved with biological combinations such as anti-IgE, anti-IL5/IL-5R, and anti-IL-4R.However, studies with these combination treatments are needed in this CRSwNP eosinophilicsevere asthma phenotype to achieve this." (PMID 40145823, 2025). "IL-5 is important in eosinophilic differentiation and survival, and it serves a pivotal function in eosinophilic inflammation in asthma." (PMID 40893770, 2025). "Studies have indicated that transforming growth factor beta (TGF-β) and Th2 cytokines (IL-5 and IL-13) contribute to airway remodeling as asthma progresses." (PMID 40558541, 2025). "Depemokimab is an ultra-long-acting anti-IL-5 antibody with promising results in phase III trials as a twice-yearly biologic for T2-high asthma." (PMID 40364184, 2025). "The Th2 subpopulation, which generates IL-4, IL-5, IL-9 and IL-13, contributes to asthma disease pathogenesis." (PMID 40095032, 2025). "Asthma is triggered by a variety of cytokines (such as IL-4, IL-5, IFN-γ, etc.)and inflammatory medium chronic inflammatory disease of the airway." (PMID 40563981, 2025). "Asthma is characterized by the coordinated increase in IgE production induced by IL-4 and the rise in eosinophils induced by IL-5, both releasing granular substances that drive inflammation and bronchoconstriction." (PMID 41309530, 2025). "Following anti-IL-5 monoclonal antibody therapy, patients with inactive RA and concomitant asthma had an exacerbation of disease, which is logically clarified by REs loss." (PMID 40786589, 2025). "In recent years, biologic therapies have been designed to address IL-4, IL-5, and IL-13, key components of type 2 inflammation, in severe asthma patients." (PMID 40303400, 2025). "Although the importance of IL-5 and eosinophils in asthma was initially uncertain, studies using anti-IL-5 mAbs confirmed their key roles in it;20,21 as such, IL-5 was identified as a suitable therapeutic target for SEA." (PMID 41458996, 2025). "The current biologics for severe asthma treatment include omalizumab (anti-IgE), mepolizumab and reslizumab (anti-IL-5), benralizumab (anti-IL-5 receptor), dupilumab (anti-IL-4/IL-13), and tezepelumab (anti-TSLP)." (PMID 40364184, 2025). "Galectin-9 has demonstrated efficacy in a Dermatophagoides farinae allergen-induced asthma model by suppressing the expression of IL5, IL13, CCL11, CCL17, reducing eosinophilia, and pulmonary hyperresponsiveness." (PMID 41516283, 2025). "Depemokimab (ultra-long-acting anti-IL-5) is showing promising results in the treatment of severe asthma with an eosinophilic phenotype." (PMID 40364184, 2025). "This suggests that GEB treatment has an anti-inflammatory and anti-allergic effect by reducing the levels of IgE and the cytokines IL-4, IL-5, and IL-13 and ameliorating histopathological changes in an asthma rat model." (PMID 40958130, 2025). "Upon stimulation, they produce IL-5 and IL-13, thus contributing to the progression of changes in asthma." (PMID 40723867, 2025). "While T2 inflammation, driven by cytokines like IL-4, IL-5, and IL-13, is common in childhood asthma, non-T2 asthma, characterized by neutrophilic or pauci-granulocytic patterns, also exists." (PMID 40486460, 2025). "In the clinical management of severe asthma, biological agents (such as anti-IgE antibodies, anti-IL-5/IL-5R antibodies, etc.)are key therapeutic approaches targeting specific inflammatory phenotypes, particularly T2 inflammation." (PMID 41244254, 2025). "Activation of eosinophils in the respiratory system is central to the pathophysiology of asthma and, through prevention of recruitment and activation of eosinophils, IL-5 inhibitors interrupt the cascade of inflammation." (PMID 40283665, 2025). "Despite the efficacy of inhaled corticosteroids and biologics targeting IL-4 or IL-5 in many asthma patients, a significant subset still experiences poor asthma control, highlighting the need for complementary therapeutic approaches." (PMID 40430465, 2025).
asthma (continued). "By blocking IL-5, mepolizumab reduces the recruitment and activation of eosinophils in the airway, which can alleviate inflammation and reduce asthma exacerbations." (PMID 40564060, 2025). "IL-5 and IL-13 support eosinophil survival and recruitment, and program type 2 T helper cell responses in allergy and asthma." (PMID 40821845, 2025). "Recent studies have provided substantial evidence that Th2 cell-related cytokines, such as IL-4, IL-5 and IL-13, play a pivotal role in the development and severity of asthma." (PMID 40323927, 2025). "A small cohort of patients treated with benralizumab demonstrated that patients with elevated sputum interleukin-5 were more likely to achieve better asthma control and lung function." (PMID 40863432, 2025). "The potential importance of GPR183 has recently been suggested by a clinical study in asthma patients, which found that the therapeutic efficacy of anti-IL-5 treatment correlated with reduced GPR183 expression on type 2 lymphocytes." (PMID 40766699, 2025). "Traditionally, IL-5 has been well-characterized for its role in eosinophilic inflammation in asthma pathophysiology." (PMID 41188935, 2025). "Type 2 (T2) inflammation represents the predominant immunological pathway in asthma and is characterized by eosinophilic airway infiltration together with Th2-dependent overproduction of cytokines such as IL-4, IL-5, and IL-13." (PMID 41515904, 2025). "These biomarkers reflect the underlying immunopathology driven by cytokines such as interleukin-4 (IL-4), interleukin-5 (IL-5), and interleukin-13 (IL-13), which are key therapeutic targets in modern asthma management." (PMID 41149833, 2025). "IL-5 inhibitors seemed to show a more pronounced increase in asthma control than IL-4/IL-13 inhibitors with MDs of −0.4 and −0.2, respectively." (PMID 39844912, 2025). "Biologic agents such as omalizumab (anti-IgE), mepolizumab and benralizumab (anti-IL-5/IL-5R), and dupilumab (anti-IL-4Rα) are effective options for T2-high asthma, reducing exacerbations with good safety profiles." (PMID 41318536, 2025). "IL-4 is involved in activating inflammation in type 2-high asthma and stimulates mast cells to further release IL-4, IL-5 and IL-13." (PMID 41371716, 2025). "We searched for “ CRSwNP”, “asthma”, “biologic therapies”, “Anti-IL-4RA”, “Dupilumab”, “Anti-IgE”, “Omalizumab”, “Anti-IL-5”, “mepolizumab” from 2024 to 2000." (PMID 40230787, 2025). "Our transcriptomic analysis further suggests that IL-5 amplifies fibroblast responsiveness to surrounding cytokines, particularly in T2-high asthma, where IL-5 levels are elevated." (PMID 41188935, 2025). "We examined the correlations of serum IL-36 levels with serum IL-6, IL-8, IL-10, IL-13, IL-17, IFN-γ, and TNF levels, except for IL-4 and IL-5 levels, which were only rarely observed in our asthma patients." (PMID 40115968, 2025). "T2-high asthma is defined by eosinophilic inflammation and elevated levels of T helper 2 (Th2) cytokines, mainly IL-4, IL-5, and IL-13." (PMID 40355861, 2025). "All the anti–IL-5 and anti–IL-4/IL-13 therapies tested in the included studies showed beneficial effects in terms of lung function, asthma control, and reducing the rate of exacerbations." (PMID 39844912, 2025). "In this study, we concentrated on type 2 inflammation in asthma and discovered that diminished diversity of lung microbiota correlates with elevated levels of IL-5 and eosinophil percentage (EOS%)." (PMID 39932326, 2025). "Our findings provide novel insights into the pro-fibrotic role of IL-5 in asthma, highlighting its potential contribution to airway remodelling and suggesting new therapeutic targets and outcomes for intervention." (PMID 41188935, 2025). "As reported, IL-4, IL-5, and IL-13 are proinflammatory cytokines; eotaxin is a pivotal chemokine crucial for eosinophil homing to the lungs of asthma patients; and CCL4, CCL5, MCP-1, and GM-CSF recruit macrophages." (PMID 40050290, 2025).
asthma (continued). "Studies have shown that both biologic IL-5 therapy effectively reduce the need for oral glucocorticosteroids, improve asthma control, and diminish the presence of eosinophils in the blood." (PMID 40862698, 2025). "Type 2 cytokines, such as: IL-4, IL-5 and IL-13, as well as IL-8 play a significant role in asthma development." (PMID 40389545, 2025). "Other biologics such as Benralizumab (anti-IL-5Rα), Dupilumab (anti-IL-4Rα), Mepolizumab (anti-IL-5), and Reslizumab (anti-IL-5) have been used in asthma patients and have demonstrated positive therapeutic effects in some cases." (PMID 41309530, 2025). "IL-5 not only functions as the main growth factor for eosinophils, but in a severe asthma model, it was observed to enhance the pro-fibrotic roles of eosinophils through the transforming growth factor beta (TGF-β) pathway." (PMID 41007770, 2025). "In people with asthma, researchers found a link between BMI and the inflammasome response, with increased levels of IL-5 and IL-13." (PMID 41007770, 2025). "From a physiological mechanism perspective, estrogen exerts a direct protective effect on asthma by inhibiting Th2-type inflammatory responses (e.g., reducing the release of IL-4, IL-5, and IL-13) and lowering airway hyperresponsiveness." (PMID 41244254, 2025). "By targeting IL-5, current biological therapeutics aim to suppress the activity of eosinophils and suppress asthma." (PMID 40723867, 2025). "GPR183 levels in type 2 lymphocytes were reported to be strongly correlated with asthma outcomes following anti-IL-5 antibody treatment, highlighting the potential importance of GPR183 in regulating pulmonary type 2 immunity." (PMID 40766699, 2025). "Tc2 levels, particularly IL‐5+ and IL‐9+ Tc cells, peaked during asthma exacerbations at ~25% of circulating Tc cells, rivalling the quantitative increases observed for Th cells." (PMID 40016948, 2025). "On the other hand, EC growth in joints was decreased when a monoclonal antibody neutralized IL-5, preventing the resolution of asthma-induced arthritis." (PMID 40786589, 2025). "Reslizumab is a humanized monoclonal IL-5 antibody developed by Teva Pharmaceuticals that has been approved in the USA for patients aged ≥18 years as add-on maintenance treatment for severe asthma with an eosinophilic phenotype." (PMID 40564060, 2025). "The development of eosinophils is regulated by cytokines such as IL-5 and GM-CSF, which promote the proliferative properties of inflammatory-like and lung-resident-like eosinophils in the blood of asthma patients." (PMID 40636260, 2025). "Inhibition of CRTh2 activation has been proposed as a treatment strategy for asthma inflammation by inhibiting the release of critical cytokines, including IL-5, IL-4, IL-13, IL-33, and IL-25, and blocking eosinophil and basophil degranulation." (PMID 40283665, 2025). "Eosinophils, important cells in the progression of asthma and remodeling of the airways, can be activated by IL-5 and then migrate into the allergic airways." (PMID 40343297, 2025). "In asthma patients, IL-4 and IL-5 are secreted, which generate eosinophils and induce airway inflammation and airway remodeling." (PMID 40958130, 2025). "Depleting eosinophils with anti-IL-5 therapy reduces BMI in patients with obesity and severe asthma." (PMID 41007770, 2025). "Both anti-IgE and anti-IL5/IL5R treatment demonstrated significant reductions in exacerbations in patients with severe asthma, possibly preventing elevated CV risks after exacerbations and avoiding the need for OCS bursts." (PMID 40823190, 2025). "Th2 biomarkers such as IgE and IL-5 are established predictors of therapeutic response to biologics in adults, yet their prognostic utility across asthma stages is limited in the pediatric asthma cohort." (PMID 40503233, 2025). "Anti-IL-5-blocking antibodies have been used to achieve this, and animal asthma models, including primates, are inhibited by these antibodies in terms of eosinophilic inflammation and AHR." (PMID 40136649, 2025).
asthma (continued). "In patients with asthma, peripheral blood eosinophilia is recognized as the most important biomarker for predicting the efficacy of biologics targeting IL-5." (PMID 40978168, 2025). "Salidroside has also been reported to alleviate inflammatory cell infiltration in OVA-induced asthma mouse models, suppress IL-4, IL-5, and IL-13 expression, and reduce phosphorylation of Akt and GSK3β." (PMID 40490797, 2025). "Asthma, marked by inflammation driven by type 2 helper T (Th2) cells and cytokines like IL-4, IL-5, and IL-13, also involves Th17 cells and IL-17 in more severe instances." (PMID 40661126, 2025). "Among these, Type 2-high (Th2-high) asthma is the most well-characterized in both children and adults, driven by IL-4/IL-5/IL-13-mediated eosinophilic inflammation and elevated fractional exhaled nitric oxide (FeNO)." (PMID 40503233, 2025). "Severe asthma pathophysiology is essentially Type 2 (T2) inflammation-dominated, with the major cytokines, interleukin-4 (IL-4), IL-5, and IL-13 involved." (PMID 40283665, 2025). "Th2 cells secrete cytokines such as IL-4, IL-5, and IL-13, which promote IgE production and eosinophil infiltration, thereby triggering asthma symptoms." (PMID 40417314, 2025). "Two major endotypes are T‐helper type 2 (TH2)‐high asthma, characterized by eosinophilic inflammation and elevated cytokines (IL‐4, IL‐5, IL‐13, IgE), and TH2‐low asthma with neutrophilic or pauci‐granulocytic profiles and corticosteroid‐resistance." (PMID 41185941, 2025). "The pathogenesis of asthma is closely related to the overactivation of the Th2 cell immune response, which leads to the production of type 2 cytokines such as IL-4 and IL-5." (PMID 40430465, 2025). "Mepolizumab, a humanized monoclonal antibody specifically targeting IL-5, has gained global approval as an add-on therapy for severe asthma patients who exhibit an eosinophilic phenotype." (PMID 40236701, 2025). "Biologic therapies targeting cytokines IL-4, IL-5, and IL-13 have been shown to provide benefits to asthmatic patients over currently existing asthma treatments." (PMID 39844912, 2025). "This was an observational study of 91 severe type-2 high asthma patients recruited from a tertiary asthma clinic, of whom 67 subsequently started anti-IL5 or anti-IL5R biologics." (PMID 39922604, 2025). "Th2 cells are mainly responsible for the allergic responses and asthma, as they secrete cytokines such as IL-4, IL-5, and IL-13." (PMID 39060348, 2024). "While taking inspiration from its pathogenesis, anti-IL-5 drugs would be beneficial in cases of eosinophilic profiles in patients, such as a 27-year-old woman suffering from both asthma and CSU." (PMID 39062104, 2024). "Based upon these findings, we can now prescribe anti-IL-5 Abs/anti-IL-5R Abs to patients with eosinophil-predominant severe asthma." (PMID 38785953, 2024). "Anti-TSLP and anti-IL5 were the most frequently used biologics for patients with type 2 low asthma (14% and 9%, respectively); however, most (70%) type 2 low phenotype patients were not treated with biologic agents." (PMID 38637825, 2024). "Asthma, aspirin intolerance, peripheral eosinophilia, IL-5 expression, T2 profile, and intense sinus opacification have been noted as independent predictors of the condition in different studies." (PMID 39328679, 2024). "Asthma is also a disease with a second type cytokine pattern, in which the levels of cytokines in this group, especially IL-4 and IL-5, increase in response to allergens, leading to the inflammatory state of asthma." (PMID 38918842, 2024). "Because anti-IL-5 therapy is included in EU for adults with eosinophilic phenotype severe asthma as an add-on treatment, she was treated with mepolizumab 100 mg, every 4 weeks." (PMID 39062104, 2024). "In asthma, increased levels of IL-5 promote the accumulation of eosinophils in the airway walls and contribute to airway inflammation." (PMID 39407835, 2024).
asthma (continued). "Th2 cells, which predominate in allergic reactions and asthma, are the primary source of the type 2 cytokines IL-4, IL-5, and IL-13." (PMID 38731707, 2024). "For example, IL-5 levels were elevated in the overweight/obese asthma group compared to normal-weight asthma group, however there was no corresponding increase in blood eosinophil count." (PMID 39902293, 2024). "In autoimmune asthma, IL-5 promotes the immigration of eosinophils into the airways, leading to tissue damage and worsening asthma symptoms." (PMID 39407835, 2024). "Because eosinophil count is associated with severe asthma exacerbations and overall asthma control, IL-5 is closely related to asthma management." (PMID 39200350, 2024). "We have reported that among severe asthma cases with high FeNO (>27 ppb) and a low blood eosinophil count (<265 cells/μL), with the treatment including an anti-IL-5/IL-5R Ab, almost half of the cases demonstrated sputum eosinophilia (>2.7%)." (PMID 38785953, 2024). "CD125 is a receptor for IL-5, a key mediator of allergic diseases, including allergic rhinitis and asthma." (PMID 38534377, 2024). "Activated eosinophils secrete a variety of cytokines during the development of asthma, including Th2 cytokines (IL-4 and IL-5), acute proinflammatory cytokines (e.g., TNF-α, IL-6, and IL-8) and chemokines." (PMID 38245791, 2024). "Higher sIL-5Rα levels in eCOPD patients compared to severe asthma patients indicate enhanced receptor cleavage of cell membranes and the neutralization of IL-5 in patients’ blood." (PMID 39766355, 2024). "This is consistent with our patients being predominantly referred to departments of respiratory medicine with an ANCA-negative, “eosinophilic-driven” phenotype of EGPA, and the use of anti-IL-5/Rα biologics in severe asthma." (PMID 38585151, 2024). "Th2 cells play a critical role in asthma development, secreting the pro-inflammatory type 2 cytokines IL-5 and IL-13." (PMID 39459021, 2024). "The pathophysiology of asthma is based on the elevated level of cytokines like IL-4, IL-5, and IL-13 production from Th2 cells." (PMID 39118763, 2024). "The expression level of IL5RA in IL‐5‐activated eosinophils and the levels of IL17RA and CRTH2 in IL‐5 or IL‐17‐activated eosinophils were significantly higher for patients with asthma than for normal individuals." (PMID 39575691, 2024). "The acknowledgment that asthma is a heterogeneous disease has prompted pharmaceutical companies to develop new drugs to specifically target eosinophils, IL-5, IL4 receptor, and IgE involved in different types of asthma." (PMID 39459021, 2024). "Compared to patients treated with anti-IgE therapy, those who subsequently received anti-IL5/5R therapy tended to have later onset disease and have more severe asthma in terms of exacerbation rate and LTOCS use." (PMID 38711495, 2024). "These particles also induce the release of IL-5 and IL-13, which play an important role in allergic airway diseases such as asthma, while stimulating type 2 ILCs to produce excess IL-5 and IL-13, leading to airway hyperresponsiveness." (PMID 38524119, 2024). "For example, IL-5+ ILC2s in the peripheral blood and sputum of severe asthma patients are increased as compared to those with mild asthma or control patients." (PMID 38785953, 2024). "The distinct sIL-5Rα levels in eCOPD and severe asthma patients suggest differentially regulated IL-5 signaling pathways." (PMID 39766355, 2024). "The relative specificity of this receptor for eosinophils among circulating granulocytes suggested monoclonal antibodies against IL-5 and IL-5Rα as a strategy to mitigate eosinophil-driven pathology in asthma." (PMID 40047886, 2024). "The epithelial-derived alarmin TSLP significantly promotes eosinophil-lineage commitment and differentiation, especially when combined with IL-5 in vitro, suggesting that bronchial epithelial cells contribute to persistent eosinophilic inflammation in asthma." (PMID 39518415, 2024).